HDAC4 (histone deacetylase 4)
Diseases named in the same sentence as HDAC4 in open-access papers (continued):
Sharing a sentence is not in itself a finding about the gene and the disease.
glioma (continued). "HDAC4 expression is downregulated in glioblastoma compared with other gliomas and normal brain tissue, although there is considerable variation in its expression levels between resected tumors from glioblastoma patients and other gliomas." (PMID 28424758, 2017). "Based on these results, we propose that low HDAC4 expression is a characteristic of high-grade glioma." (PMID 25557107, 2015). "The results of the present study reveal that HDAC4 is a strong prognostic factor in glioma and likely determines patient outcome via modulation of genomic integrity." (PMID 25557107, 2015). "HDAC4 and/or HDAC5 have been linked to tumorigenesis, tumor progression or chemoresistance in a variety of cancers, such as colon, urothelial, gastric, haematological, pancreatic, esophageal, or glioma." (PMID 36982651, 2023). "The upregulation of HDAC4 in glioma cells supports tumorigenesis." (PMID 31905609, 2019). "HDAC4 inhibitors could be an essential link to developing targeted treatment for glioma tumors or studying the role of HDAC4 in cancer research." (PMID 31905609, 2019). "With immunohistochemistry being widely used in both routine clinical practice and research, the role of HDAC4 in glioma could be further validated from protein level in the near future." (PMID 25557107, 2015). "Moreover, the predictive value of the O-6-methylguanine-DNA methyltransferase (MGMT) promoter methylation status—a widely used glioma marker—was refined by HDAC4 expression level, which was significantly related to CIN in our study." (PMID 25557107, 2015). "However, previous studies reported that HDAC4 was significantly upregulated in glioma tissues." (PMID 35545840, 2022). "However, previous studies have reported that HDAC4 is significantly upregulated in glioma tissues." (PMID 36227941, 2022). "Ten glioma samples (5 IDH1 wildtype and 5 IDH1 mutant) were stained for various HDAC genes using internally validated antibodies (HDAC1, HDAC2, HDAC3, HDAC4, HDAC5, HDAC6 and HDAC7) and scored by a blinded neuropathologist (AK)." (PMID 37528157, 2023). "Then, using six HDAC genes (HDAC1, HDAC3, HDAC4, HDAC5, HDAC7, and HDAC9), we established a prognostic model for glioma patients, and this prognostic model was validated in an independent cohort population." (PMID 35545840, 2022). "For instance, HDAC4 and HDAC6 have been indicated to make glioma cells resistant to radiation by maintaining DNA double-strand damage repair and stemness." (PMID 35193602, 2022). "Then, using six HDAC genes (HDAC1, HDAC3, HDAC4, HDAC5, HDAC7, and HDAC9), we established a prognostic model for glioma patients, and this prognostic model was validated in an independent cohort." (PMID 35545840, 2022). "A model based on six HDAC genes (HDAC1, HDAC3, HDAC4, HDAC5, HDAC7, and HDAC9) can predict the overall survival of glioma patients well and these genes are potential therapeutic targets." (PMID 35545840, 2022). "In contrast, under-expressed HDAC4, HDAC5, and HDAC11 ranking within the top 1% gene rank were observed in glioma." (PMID 34540896, 2021). "Differentially expressed HDAC family members were identified with significance in ONCOMINE, namely the upregulated HDAC1 and HDAC6, as well as the downregulated HDAC4, HDAC5, and HDAC11 in glioma." (PMID 34540896, 2021). "Thus, inhibition of HDAC4 may present an option to develop a targeted therapeutic for glioma." (PMID 31905609, 2019). "Thus, the development of HDAC4 inhibitors could present a novel therapeutic route for glioma." (PMID 31905609, 2019).
glioma (continued). "Among all patients studied,the expression of HDAC1 and HDAC3 was inversely correlated withsurvival, whereas the expression of HDAC4, HDAC5, HDAC6,HDAC11 and SIRT1 was significantly and positively correlated withsurvival time of patients with gliomas." (PMID 25791281, 2015). "Along the same line, glioma samples (ODsand GL) with high HDAC4 and SIRT1 expression were metabolomicallydifferent from samples with low HDAC4 and SIRT1 expression, thelatter having a significantly lower GPChol/PChol ratio than the former group(respectively)." (PMID 25791281, 2015). "HDAC4 expression and CIN were closely related in glioma from both functional and statistical standpoints." (PMID 25557107, 2015). "In conclusion, in present study, HDAC4 expression was found to be closely related to tumor grade and patient prognosis, and functional and statistical analyses identified a correlation between HDAC4 expression and CIN signature in glioma." (PMID 25557107, 2015). "We also identified that HDAC1 and HDAC3expression levels were negatively correlated with survival time among gliomapatients, whereas the expression of HDAC4, HDAC5, HDAC6,HDAC11 and SIRT1 was positively correlated with survival time ofpatients with gliomas." (PMID 25791281, 2015). "The fact that HDAC4 and MAP2K7 are expressed at high levels suggests that the cancer-promoting effects of MAP2K7 in glioma cells could be stopped using drugs that inhibit HDAC4." (PMID 39717752, 2024). "We first performed the univariate cox regression and found that the elevated expressions of HDAC7, HDAC3, and HDAC1 were associated with poor prognosis while increased expressions of HDAC6, HDAC5, HDAC4, and HDAC11 were favorable for prognosis in low-grade glioma." (PMID 36227941, 2022). "Similar to HDAC4, HDAC5 was also found to be expressed at low levels in glioma tissue." (PMID 35545840, 2022). "Like HDAC4, HDAC5 has also been found to be down-expressed in glioma tissues." (PMID 36227941, 2022). "These miR-637-targeted genes include HMGA1, CDK6, and WNT7A in glioma, HEMGN in PTC, APLN in GC, USP21 in HCC, LY6E and CTSB in CHOL, NUPR1 in OSCC and MM, HDAC4 in SaOS, ABL1 in CML, KLK4 in OC, PLXNB2 in OC, AKT1 in TNBC, PTC, and HCC, AKT3 in TNBC, and RING1 in CCa." (PMID 36175921, 2022). "These genes include HMGA1 in glioma, AKT1 in glioma, PTC, GC, and HCC, HEMGN in PTC, APLN and MMP19 in GC, WNT1 in CRC, NUPR1 in CRC and OSCC, LY6E and CTSB in CHOL, KLK4 and PLXNB2 in OC, and HDAC4 and STAT3 in SaOS." (PMID 36175921, 2022). "HDAC4 upregulation was significantly correlated with poor OS and DFS in all patients with glioma." (PMID 35359455, 2022). "This suggests a significant relationship between HDAC4 expression and CIN in glioma." (PMID 25557107, 2015). "The role of HDAC4 in specific cells (HeLa (cervical cancer), U373 (glioma), OVCAR (ovarian), T98G (glioma), HCT116 (colorectal), NHA (astrocytic) and SKBR3 (breast)) and tissues (cerebral cortex, testis, prostate, and the epidermal layer of the skin) is becoming more clear." (PMID 24896240, 2014). "It is conceivable, that in gliomas high levels of HDAC4 expression in complex with MEF2 acts as transcriptional repressor of KLF4 and, consequently, of zonula occluden-1, claudin-5, and occludin gene expression, which may be another important component in the mechanism of BBB disruption in gliomas." (PMID 30837601, 2019). "qPCR was adopted to detect the expression of HDAC1, HDAC3, HDAC4, HDAC5, HDAC7 and HDCA9 in nontumor and glioma tissues." (PMID 35545840, 2022). "However, the expression levels of HDAC4 and HDAC5 were lower in the glioma patients than in the nontumor control groups." (PMID 35545840, 2022).
hepatocellular carcinoma (24 papers, 2012 to 2025). A malignant tumor that arises from hepatocytes. "This process underlies the crosstalk between microRNAs and lncRNAs in hepatocellular carcinoma, where overexpression of histone deacetylase-4 (HDAC4) inhibits miRNA-200a and vice versa." (PMID 37245177, 2023). "HDACs 4 and 5 are associated with liver injury and the development of hepatocellular carcinoma, and we previously found greater HDAC4 expression in rat soleus muscle during tail suspension after 8‐week physical inactivity intervention." (PMID 37226378, 2023). "HDAC4 inhibition as a potential interventional strategy to treat liver diseases has been implicated in models of non-alcoholic steatosis and hepatocellular carcinoma, both of which feature fibrosis as a key pathophysiological process." (PMID 28548935, 2017). "In hepatocellular carcinoma-resistant patients, histone deacetylase 4 (HDAC4) modifies the chromatin configuration within the SPRY4 promoter region, leading to transcriptional inhibition of the SPRY4 gene." (PMID 38686189, 2024). "The polyamine spermidine can improve MAP1s instability induced by HDAC4 and inhibit the occurrence of cirrhosis and hepatocellular carcinoma by promoting autophagy." (PMID 35637410, 2022). "On the contrary, our data shows direct interactions among FOXO1, HDAC3, and HDAC4 in HepG2 which is a well-differentiated hepatocellular carcinoma of humans." (PMID 30424007, 2018). "miR-22 downregulation participated in tumorigenicity and progression of hepatocellular carcinoma cells through upregulating histone deacetylase 4 (HDAC4) expression." (PMID 28882183, 2017). "The HDAC4/Sp1/miR-200a regulatory network responsible for the downregulation of miR-200a enhances the proliferation and migration of hepatocellular carcinoma cells." (PMID 24830600, 2014). "Sp1 can recruit HDAC4 to the promoter of miR-200a, resulting in silencing of miR-200a and promoting the proliferation and migration of hepatocellular carcinoma cells." (PMID 24830600, 2014). "We show increased m6A-modifications of HDAC4 in ALKBH5 silenced cells that may influence HIF-α protein stability in our hepatoma model as previously reported in pancreatic cancer." (PMID 38227578, 2024). "To investigate whether ALKBH5 regulates HDAC4 m6A modifications in HepG2-NTCP hepatoma cells we precipitated methylated HDAC4 mRNA in ALKBH5 silenced cells under hypoxic conditions." (PMID 38227578, 2024). "Likewise, SPRY4 suppression occurs in hepatocellular carcinoma drug-resistant patients, where histone deacetylase 4 (HDAC4) modifies the histone configuration within the SPRY4 promoter region, resulting in a heterochromatin (silenced) state." (PMID 36384366, 2023). "Similarly, HDAC4 targeted by miR-1-1 was upregulated in human hepatocellular carcinoma cells and primary hepatocellular carcinoma." (PMID 22414492, 2012). "In contrast, as a target gene relevant to execution and completion of apoptosis, the overexpressed CDKN1A triggered by HBx-induced HDAC4 inhibition was concordant with the earlier research that HBx can relieve a block on CDKN1A expression and prolong G1→S transition in human hepatoma cells." (PMID 32878239, 2020). "miR-22 downregulation was related to poor survival in hepatocellular carcinoma (HCC) patients, which may be due to the upregulation of histone deacetylase 4 (HDAC4), a potential miR-22 target." (PMID 30041677, 2018). "Whereas HDAC7, and to a lesser extent HDAC4, appear to repress HBV transcription, HDAC5 upregulated HBV capsid abundance and supported enhanced HBV biosynthesis in both hepatoma and nonhepatoma cells." (PMID 32822428, 2020).
prostate carcinoma (23 papers, 2010 to 2025). A carcinoma that arises from epithelial cells of the prostate gland. "In chondrosarcoma, a decrease in HDAC4 expression leads to the upregulation of vascular endothelial growth factor expression, thereby stimulating angiogenesis; in prostate cancer cells, HDAC4 downregulation was associated with a high level of androgen receptor expression, which promoted cell growth." (PMID 25557107, 2015). "For example, a deacetylase, histone deacetylase 4 (HDAC4) is up‐regulated in prostate cancer cell lines and regulates the expression of cell cycle‐related genes through deacetylation, thereby promoting tumour cell proliferation and malignant transformation." (PMID 39778006, 2025). "Tasquinimod (TasQ) is a highly selective inhibitor of HDAC4 and also a clinically tested oral antiangiogenic agent against castration-resistant prostate cancer." (PMID 34445342, 2021). "Previous study also suggested that HDAC mediates miRNA-1 expression, which was indicated by the evidence that HDAC4 silencing induced miRNA-1 expression in human adenocarcinoma (A549) and human prostate cancer (DU-145) cell lines." (PMID 31157242, 2019). "It is exciting that four compounds – used in other diseases such as prostate cancer – targeted HDAC4 activity, reversed the impaired expression of the HDAC4-controlled genes and subsequently ameliorated pertubations in autophagy and lysosomal pathways." (PMID 31024227, 2019). "HDAC4 has also been shown to help prostate cancer cells overcome hypoxic conditions by stabilizing HIF-1α." (PMID 29882797, 2018). "HDAC4/6 has the potential to help prostate cancer cells overcome hypoxic conditions by stabilizing HIF-1 α." (PMID 29882797, 2018). "The protective effect of Nrf2 on HDAC4 was reported to precede HDAC4-mediated downregulation of the microRNAs miR-206 and miR-1 in lung and prostate cancer cell lines." (PMID 28424758, 2017). "The differences observed between the two studies are most likely due to changes in HDAC4 expression in response to the development of the aggressive phenotype of late stage prostate cancer." (PMID 25322459, 2014). "Tasquinimod treatment phenocopies HDAC4 knock down with regard to inhibition of prostate cancer cell survival signaling and endothelial angiogenesis under stressful hypoxic conditions." (PMID 25193858, 2014). "Binding to HDAC4 is relevant since prostate cancer cells over express this protein and are inhibited in their adaptive survival response to a stressful microenvironment when transcription of this gene is knocked down resulting in their loss of tumorigenic ability." (PMID 25193858, 2014). "Also, we previously reported that YY1 and the histone deacetylase 4 (HDAC4) affected prostate cancer cell growth by repressing HOXB13 transcription through histone modification." (PMID 22808286, 2012). "In prostate cancer, a circular RNA called hsa_cir_0003258 bound to IGF2BP3 in the cytoplasm, leading to increased stability of HDAC4 mRNA and promoting cancer metastasis." (PMID 38760723, 2024). "Among class II HDACs, HDAC-4 and HDAC-5 were significantly overexpressed in prostate cancer tissues and even more in the cases of recurrent prostate cancer." (PMID 34441281, 2021). "Previous experimental work have already shown that miR-146b and miR-206 are prostate cancer related miRNAs and targeting ROCK1 and HDAC4, respectively." (PMID 24267745, 2013). "Importantly, we found that the HDAC4/MybL1/YAP pathway is also present in colon and prostate cancer cells, consistent with our observations in pancreatic cancer cells." (PMID 41281751, 2025). "Previously, we developed novel amide-bearing hydroxamic acid derivatives as class-selective HDAC inhibitors termed SL142 and SL325 and reported that these small molecules show more significant HDAC1, HDAC4 and HDAC6 inhibitory activity in human prostate cancer cells LNCaP than SAHA." (PMID 21079797, 2010). "YY1 and HDAC4 complex represses HOXB13 gene in AR negative prostate cancer cells." (PMID 31824839, 2019).
colon cancer (22 papers, 2011 to 2025). "Class IIa HDACs are also involved in the programmed cell death, e.g., HDAC4 knockdown in colon cancer induced apoptosis, which was associated with increased p21 expression." (PMID 36982651, 2023). "Overall, we here demonstrtae a role for HDAC-4 in regulating differentiation and growth properties of colon cancer cells in causal association with EGFR/ERK1/2-signaling and claudin-2 expression." (PMID 29152115, 2017). "We have documented similar association between HDAC-4 and claudin-2 expression in colon cancer cells undergoing spontaneous or HDACi-induced differentiation." (PMID 29152115, 2017). "In current studies, we have identified the role of class-II HDAC, HDAC-4 in regulating claudin-2 expression in causal association with differentiation in colon cancer cells." (PMID 29152115, 2017). "In HCT116 colon cancer cells, downregulation of HDAC4 expression was shown to inhibit growth, induce apoptosis, reduce xenograft tumor growth, and increase p21 transcription." (PMID 38473392, 2024). "Recently, accumulating evidence has shown that HDAC4 overexpression is correlated with the development and progression of cancers, including multiple myeloma, prostate cancer, breast cancer, colon cancer, glioblastoma, and esophageal cancer." (PMID 33542203, 2021). "HDAC4 is a transcriptional repressor and its inhibition was found to reduce the growth of colon cancer cells through upregulation of p21." (PMID 34550356, 2021). "Taken together, our data demonstrated role of the HDAC4/EGFR/ERK1/2 signaling in regulating claudin-2 expression in differentiating colon cancer cells." (PMID 29152115, 2017). "It will be interesting to determine the role of HDAC4/EGFR/ERK1/2 signaling in colon cancer expressing wild type K-Ras versus mutant K-Ras, in association with cancer progression and therapy resistance, in future studies." (PMID 29152115, 2017). "Accordingly, colon tumors demonstrated marked upregulation of the HDAC-4/ERK1/2/Claudin-2 signaling." (PMID 29152115, 2017). "We have documented maximal claudin-2 and HDAC-4 expression in the proliferative compartment in mouse colonic epithelium and colon tumors in APCmin mice." (PMID 29152115, 2017). "This repression of HDAC4 by cisplatin was also observed in vivo in fragments of human colon cancer xenografted in nude mice." (PMID 27935863, 2017). "Our demonstration of an important role for HDAC-4 and claudin-2 in colon cell growth would suggest that inhibitors of class-I and -II HDACs are likely to be more efficient at inhibiting colon cancer cell growth than class I-specific inhibitors." (PMID 29152115, 2017). "In colon cancer cells, miR-22 reduces HDAC4 levels, which impairs cancer progression." (PMID 36762207, 2023). "In colon cancer cells miR-22 reduces HDAC4 levels, affecting the progression of the cancer." (PMID 36762207, 2023). "In addition, it has been suggested that miR-140-5p plays a role in the development of chemoresistance in human osteosarcoma and colon cancers by reduced cell proliferation through G1 and G2 phase arrest mediated in part through the suppression of HDAC4." (PMID 27588393, 2016). "HDAC3 activity may be dependent on the activity of class IIa HDAC4 protein, as Sp1-dependent targeting of HDAC4 to the proximal p21 promoter in colon cancer cells was shown." (PMID 23914191, 2013). "Indeed, in the colon cancer cell line HCT116, HDAC4 participates in the resistance to 5-FU (5-fluorouracil) but not to methotrexate." (PMID 31703394, 2019). "Of interest, siRNA-depletion of HDAC-4 expression in colon cancer cells has been reported not to affect expression of other HDACs." (PMID 29152115, 2017).
colon cancer (continued). "We found that inhibition of HDAC4, but not HDAC10, down-regulates the mRNA level of YAP and MybL1 in prostate and colon cancer cells." (PMID 41281751, 2025).